IL6 (interleukin 6)
Diseases named in the same sentence as IL6 in open-access papers (continued):
Sharing a sentence is not in itself a finding about the gene and the disease.
myeloma (continued). "In addition, dysregulation of IL-6 and the production of its receptor has been connected to the etiopathogenesis of several disorders, such as multiple myeloma, self-immune disorders, and carcinoma of the prostate." (PMID 38835791, 2024). "We thus explored whether co-immunoprecipitation of PARKIN with HIF-1α and HLA-G from myeloma cells could be expedited by IL-6." (PMID 38877399, 2024). "Zhang and colleagues found that multiple myeloma-derived EVs expressing miR-103a-3p inhibited osteogenesis in bone marrow-derived mesenchymal stem cells (BMSCs) and increased IL-6 secretion in multiple myeloma cells, resulting in impaired osteogenesis and exacerbated bone metastasis." (PMID 38495881, 2024). "Additionally, PTK787 impedes VEGF-stimulated myeloma cell migration and reduces MM cell proliferation and IL-6 and VEGF release when these cells are attached to BMSCs." (PMID 38900304, 2024). "The dynamics of IL-6 in PTH treatment models are simplistic compared to multiple myeloma models." (PMID 40012834, 2024). "In addition, ectopic expression of PPARγ resulted in increased cell death and decreased cell proliferation accompanied by inhibition of IL-6 production in myeloma cells." (PMID 38334807, 2024). "Moreover, the evidence of an IL-6-mediated-autocrine growth loop was then confirmed in the human myeloma cells U266." (PMID 38541700, 2024). "Interleukin-6 (IL-6) promotes myeloma cell growth and survival, inhibiting apoptosis." (PMID 39065751, 2024). "Multiple studies have shown that interleukin-6 (IL-6) is an important growth factor involved in the physiopathogenesis of multiple myeloma, and through an autocrine/paracrine form, promotes the survival and proliferation of myeloma cells." (PMID 38254747, 2024). "IL-6 has long been identified as a key growth factor for myelomas." (PMID 38520006, 2024). "In myeloma, IL-6-secreting cells can originate from either autocrine or paracrine pathways." (PMID 39664374, 2024). "The deletion of the CRNDE locus reduces the proliferative responses to IL6 in multiple myeloma cells, and possibly, in a similar manner it may play a role in T-ALL progression, as IL6 signaling is an important part of T-cell differentiation." (PMID 38336706, 2024). "Moreover, IL-6 has been reported to stimulate the in vitro growth of new myeloma cells isolated from patients." (PMID 38002012, 2023). "Similarly, hematopoietic cell kinase (HCK) has been reported to induce GAB1 phosphorylation in response to IL-6 in multiple myeloma cells." (PMID 37627207, 2023). "Dexamethasone, in particular, inhibits secretion of inflammatory cytokines by bone marrow stromal cells, such as IL-6 required for the growth of multiple myeloma (MM) cells, suggesting that immunotherapy against IL-6 could be helpful as adjuvant to treat MM." (PMID 37085802, 2023). "The independence of myeloma cells from eosinophils in later stages could be due to cell-cell contact of myeloma cells in high cell densities or the autocrine production of IL-6 or APRIL cytokines by myeloma cells." (PMID 37587450, 2023). "IgA could activate the immune function by modulating the production of key cytokines such as TNF, IL-6, and IL-2 by human myeloma cells." (PMID 37050214, 2023). "The results showed that the IL-6 gene polymorphisms did not associate with multiple myeloma susceptibility." (PMID 38024543, 2023). "IL-6 also plays a major role in bone resorption by myeloma cells." (PMID 37120508, 2023). "In addition, TNFα can induce anemia in patients with MM by directly inhibiting the formation and differentiation of red blood cells, reducing sensitivity to erythropoietin (EPO), and promoting IL-6 secretion by myeloma cells." (PMID 37250588, 2023). "IL-1β is produced by myeloid and megakaryocytic cells and myeloma cells and could induce osteoclast activity, mediate homing and adhesion of MMPCs in the BM, and consequently induce pro-inflammatory IL-6 signaling." (PMID 38002311, 2023).
myeloma (continued). "However, it has been reported that cytokines such as TPO, IL-6, and soluble P-selectin, which participate in myeloma progression, are also required for thrombopoiesis and megakaryocytopoiesis." (PMID 38002311, 2023). "Interleukin-6 (IL-6) is a key regulator of B cell differentiation into PCs and exerts a significant impact on the pathogenesis of PC disorders, including plasmacytoma and myeloma." (PMID 37867940, 2023). "CAM has also been reported to inhibit myeloma growth factors such as IL-6." (PMID 38039297, 2023). "Additionally, hematopoietic cell types responding to IL-6 with enhanced proliferation are typically observed in diseases such as multiple myeloma and Castleman’s disease." (PMID 35406728, 2022). "Similarly, IL-6 upregulates MnSOD in multiple myeloma and prostate cancer cells, and Nrf2 mediates hepatic IL-6 induction in vivo." (PMID 35017469, 2022). "For example, in multiple myeloma, paracrine cytokine stimulation occurs as a result of myeloma cells interacting with bone marrow, resulting in increased production of IL-6, which activates JAK2 and STAT3, all of which are required for proliferation and survival." (PMID 36008987, 2022). "The IL-6/JAK/STAT pathway is also important in myeloma and may be a good therapeutic target in myeloma." (PMID 35102139, 2022). "However, the combination of tyrosine kinase inhibitors with anti-interleukin-6 antibodies induced marked inhibition of myeloma cell proliferation at low concentrations." (PMID 35342415, 2022). "IL-1b, TNF-a, IL-6, and IL-10 may contribute to osteopenia; IL-6 and IL-10 may be responsible for gammopathies and multiple myeloma; IL-1b, TNF-a, and IL-6 may have a role in the activation of hypermetabolism." (PMID 36498496, 2022). "It had reported that IL-6 production could be induced by TNF-α in a dose-dependent manner in myeloma cells." (PMID 35342422, 2022). "Additionally, interleukin-6 has long been reported as a potent myeloma-cell growth factor in patients with aggressive MM." (PMID 36547163, 2022). "Bcl3 expression was induced by IL-6 in multiple myeloma cells, which increased apoptosis." (PMID 35327480, 2022). "Highly expressed IFITM2 participates in the type I interferon response to protect cells from viral pathogens and activates the expression and secretion of IL-6, which promotes the differentiation of B cells into plasma cells, mediating the growth of myeloma and stimulating bone resorption." (PMID 36131282, 2022). "Dex reduces IL-6 mRNA levels in myeloma cells and induces plasma cell apoptosis by blocking IL-6." (PMID 36386129, 2022). "This is supported by the essential role of caveolae in IL‐6‐triggered signaling in multiple myeloma cells, as shown by its abrogation by cholesterol depletion, and by the localization of the IL‐6 receptor and STAT3 protein to the lipid raft compartment in a prostate cancer cell line." (PMID 35451191, 2022). "IL6 is a pro-inflammatory cytokine upregulated in a number of cancers, including breast, prostate, endometrial, renal cell carcinoma, oral squamous cell carcinoma, multiple myeloma, colorectal cancer and pancreatic cancer." (PMID 36138073, 2022). "One study showed ATM-dependent DDR to induce IL-6 secretion by BM stromal cells and subsequent myeloma cell chemoresistance; probing for the specific DDR cascade may reveal targetable mechanisms for future HM therapies." (PMID 34505878, 2021). "In U266B1 (multiple myeloma) and βTC (neuroendocrine pancreatic cancer), the cost/benefit ratio of the growth factor that was knocked out (respectively, IL6 and IGF2) was high enough to enable the KO clone to spread in the WT population and induce the collapse of cooperation, at least at high FBS." (PMID 34359576, 2021). "In addition, other cytokines related to myeloma biology, including interleukins 2, 6, 17 (IL-2, IL-6, IL-17) can modulate Τregs function." (PMID 34640606, 2021).
myeloma (continued). "Although IL-6 is also produced by myeloma cells and an autocrine loop is active in MM, it is considered that it is almost exclusively produced by the BMM following the adhesion of myeloma cells to stromal and bone cells and in much higher amounts than in normal individuals." (PMID 33923357, 2021). "As part of its activities, adiponectin suppresses the production of Il-6, and therefore, its reduction may indirectly contribute to the progression of myeloma cells." (PMID 33842343, 2021). "IL-6 is required for the survival and proliferation of normal immature B cells in the BM, and it has been identified as the key growth and survival factor for myeloma cells." (PMID 34631562, 2021). "Moreover, some data have suggested that IL-6 is a factor that determines survival in MM, as it inhibits apoptosis in myeloma cells." (PMID 33808304, 2021). "It has been reported that high cell expression of IL-6 mRNA in MGUS patients may predict the development of multiple myeloma." (PMID 33808304, 2021). "For example, STAT3-dependent miR-21 transcription was observed in IL-6 stimulated myeloma cells." (PMID 33537096, 2021). "The gene set enrichment analyses (GSEAs) revealed significant upregulation of various pathways, including “positive regulation of interleukin-6 production” (p = 0.001); IL-6 drives myeloma cell survival and its secretion can be inhibited by lenalidomide therapy." (PMID 33597728, 2021). "IL-6 is known to activate osteoclast formation as well as increased myeloma cell proliferation." (PMID 34201396, 2021). "As IL-6 involvement is observed in the early stages of the disease, where the myeloma interacts with the stroma and plays a key role in cancer cell survival, anti-IL-6 therapy in the early stages of the disease may have more promising results." (PMID 33808304, 2021). "Additionally, IL-6 is known to confer resistance in myeloma cells to bortezomib, melphalan, and in particular, dexamethasone-induced apoptosis." (PMID 33777050, 2021). "Other interleukins such as IL-6 and IL-3 are also involved promoting myeloma cell differentiation." (PMID 34768861, 2021). "The endothelial marrow cells secrete interleukin-6 and promote additional myeloma cell growth." (PMID 34768861, 2021). "Taking into consideration the role of interleukin 6 in MM pathogenesis as a growth and survival factor, inhibiting apoptosis in myeloma cells, this may also explain SM22 role in tumorigenesis." (PMID 35011306, 2021). "In addition, when human myeloma cells were treated with hemin, the HO-1 induction upregulated the IL-6 secretion via p38 MAPK activation." (PMID 33912151, 2021). "The IL-6 secretion is stimulated by the interaction between myeloma cells and BMSCs." (PMID 33923357, 2021). "In multiple myeloma, suppression of IL‐6‐mediated STAT3 activation and NF‐kB inhibition could inhibit proliferation, induce apoptosis, and increase chemosensitivity." (PMID 33634982, 2021). "Patients with smouldering multiple myeloma (SMM) or indolent multiple myeloma (IMM) after targeted treatment on the IL-1/IL-6 axis using Anakinra (an IL-1 receptor antagonist; IL-1Ra) showed improvement in PFS (progression-free survival) and overall survival (OS) parameters." (PMID 33808304, 2021). "Our result was consistent with the studies that bone marrow-derived MSCs (BM-MSCs) promoted colorectal cancer progression through paracrine neuregulin 1/HER3 signalling and tumor formation of multiple myeloma by cytokine IL-6 which was delivered via MSC-derived exosomes." (PMID 33744858, 2021). "There is increasing evidence that the Interleukin-6 (IL-6) signaling pathway can be inhibited by metformin; specifically, metformin substantially reduces the expression of IL-6 receptors and promotes myeloma cell apoptosis in patients with primary myeloma." (PMID 34603199, 2021).
myeloma (continued). "This difference could be explained by the fact, that survival of myeloma cells strictly depends on continuous Interleukin-6 (IL-6) supply and thus on the activation of the STAT3 signaling pathway." (PMID 34531451, 2021). "Nevertheless, it has been suggested that the generation of human MM may be mediated by autocrine IL-6 release by myeloma plasma cells, while the production of IL-6 by bone marrow stromal cells may be paracrine." (PMID 33808304, 2021). "For example, melphalan-induced IL-6 production could be problematic given it behaves as a growth factor for myeloma and may contribute to immune escape post-ASCT." (PMID 33777050, 2021). "Notably, STAT3 activation is associated with the severity of wasting in both the C‐26 and Apcmin/+ models of cancer cachexia, and AR‐42 was previously shown to suppress the IL‐6/GP130/STAT3 signaling axis in multiple myeloma cells." (PMID 31930715, 2020). "This cytokine is known to synergise with IL-6 to support myeloma cell proliferation." (PMID 33014130, 2020). "For example, the expression of PIM2 in multiple myeloma cells could be regulated by IL-6 and TNF family cytokines, TNFα, BAFF, and APRIL." (PMID 32641749, 2020). "In addition, we found that IL6 can induce the growth of myeloma and plasma cell tumours and induce the differentiation of nerve cells and that its overexpression in inflammation sites is a main cause of anaemia and chronic inflammation." (PMID 32345291, 2020). "In turn, endothelial cells will produce IGF1 and IL6 to promote myeloma cell growth." (PMID 33634031, 2020). "During hematopoiesis, IL-6 serves as an autocrine growth factor on pluripotent stem cells residing in spleen and bone marrow, megakaryocytes, myeloid cells, plasmacytoma, and myeloma cells." (PMID 31979357, 2020). "One such signalling network involved in the pathogenesis of many B cell malignancies is modulated by the transcription factor STAT3 Multiple Myeloma cells are known to be highly dependent on ‘STAT3-mediated’ IL-6 signalling for survival in standard cell culture conditions." (PMID 32098106, 2020). "As compared to IR alone, myeloma cells treated with IL-6 plus IR showed decreased caspase-3 stimulation, annexin/propidium iodide staining, PARP [poly(ADPribose) polymerase] cleavage, and mitochondrial membrane depolarization with augmented clonogenic survival." (PMID 33198328, 2020). "Furthermore, TACI-Fc can potentiate the inhibitory effect of dexamethasone or anti-IL-6 antibody on the survival of myeloma cells." (PMID 32340409, 2020). "Additionally, interleukin-6 is released from the interaction of myeloma cells with BMSCs and promotes survival of the malignant cells." (PMID 32829378, 2020). "MSCs exposed to myeloma-derived soluble factors exhibited reduced differentiation capacity, and elevated expression of senescence-related transcripts including MM-supportive Il6/IL6." (PMID 33680918, 2020). "However, another study of human multiple myeloma cells showed a positive crosstalk between IL-6 and HO-1." (PMID 32204510, 2020). "Indeed, IL-6 has been reported to be a key growth factor for myeloma cells, and IL-6-dependent multiple myeloma cell lines have been established." (PMID 32210945, 2020). "IL6 is often considered to be involved in high fever, such as that experienced by myeloma patients." (PMID 32110485, 2020). "Interestingly, Kawano of Hiroshima University reported that IL-6 acts as a growth factor for multiple myeloma cells." (PMID 32743515, 2020). "The excess IL-6 in turn promotes the proliferation of the pre-myeloma cells." (PMID 31900383, 2020). "It was also found that TACI-Fc could significantly induce the apoptosis of primary myeloma cells cultured with components of the BM microenvironment and recombinant IL-6." (PMID 32340409, 2020). "Survival of INA-6 multiple myeloma cells depends on IL-6-mediated STAT3 activation." (PMID 32041604, 2020).
myeloma (continued). "Several autocrine or paracrine soluble factors are known to be critical for promoting the survival and growth of myeloma cells and these include interleukin 6, interferon alpha, insulin-like growth factor-1, hepatocyte growth factor, and heparin-binding epidermal growth factor-like growth factor." (PMID 32340409, 2020). "IL-6 and IL-1β are potent osteoclast activators in myeloma pathogenesis." (PMID 32587468, 2020). "Interleukin‐6 (IL‐6) is a well‐documented growth factor and therapeutic target in plasma cell myeloma, and MISTRG mice that have been modified with an additional knock‐in allele encoding human IL‐6 (MISTRG6) support multiple myeloma engraftment and growth." (PMID 31515941, 2019). "As miR-21 is an anti-apoptotic factor in cancer cells, STAT3-mediated expression of miR-21 could partly explain the IL-6-induced survival of myeloma cells." (PMID 31130718, 2019). "IL-6 may act as an autocrine growth factor in some types of multiple myelomas while some others are themselves able to produce IL-6." (PMID 31523783, 2019). "Numerous reports state that IL-6 plays an essential role in the malignant progression of multiple myeloma, whereby the engagement of IL-6 with specific surface cytokine receptors activates JAK and subsequently triggers the activation of STAT3 signaling pathways." (PMID 31402861, 2019). "IL-1β, IL-6, TNF-α, and IL-10 may cause osteopenia, IL-6 and IL-10 gammopathies and lead to multiple myeloma." (PMID 30781349, 2019). "IL-6 and other cytokines constitute an inflammatory milieu in the BM for myeloma cells." (PMID 31737046, 2019). "There may be a complex regulatory network between miRNA and IL-6 in MM that promotes the progression of myeloma." (PMID 31915680, 2019). "Interestingly, in spite of the general protective effects of PACAP, myeloma cell proliferation was suppressed both directly and indirectly through interleukin-6 suppression." (PMID 31591326, 2019). "While originally described as a growth and differentiation factor for normal B cells, the ability of IL‐6 to also stimulate the proliferation of plasma cell‐derived plasmacytoma cell lines and primary plasma cell myeloma cells was discovered shortly thereafter." (PMID 31515941, 2019). "Inhibition of IL-6 from MSC-conditioned media slowed the proliferation of DKK-1 secreting myeloma cells treated with this media, suggesting that in the myeloma environment, IL-6 increases bone resorption through promoting proliferation of DKK-1-secreting myeloma cells." (PMID 30671025, 2018). "We also found that IL-6 could increase c-Met expression, which also had been reported in myeloma cells." (PMID 30158543, 2018). "Similarly, BM cancer-associated fibroblasts (CAFs) have recently been shown to protect against PI-induced apoptosis in myeloma cells, and produce high levels of IL-6, IL-8, and TGFβ." (PMID 29765356, 2018). "A good example of SFM-DR is IL-6 mediated drug resistance in multiple myeloma." (PMID 30061485, 2018). "In 2000, a team revealed that activation of PYK2 was inhibited by IL-6 in multiple myeloma." (PMID 29455640, 2018). "Recently, we demonstrated that in multiple myeloma the overexpression of Notch ligands, Jagged1 and Jagged2, combined with the expression of Notch receptors, activates the endogenous Notch signaling, which drives IL-6 secretion." (PMID 30154786, 2018). "Furthermore, the IL-6/gp130 pathway has been found to induce miR-21 via STAT3-mediated mechanisms in human myeloma cells." (PMID 30068990, 2018). "In the study of relevance of JunB in multiple myeloma (MM), IL-6 may trigger the expression of JunB and the activation of MEK/ERK or NFKB is responsible for the induction of JunB expression and AP-1 transcriptional activity." (PMID 29545936, 2018).